GAL3ST2 (galactose-3-O-sulfotransferase 2)
Description:
Catalyzes the transfer of a sulfate group from 3'-phosphoadenylyl sulfate (PAPS) to the C-3 hydroxyl group of terminal non-reducing beta-galactosyl residues. Acts both on type 1 (Gal-beta-1,3-GlcNAc-R) and type 2 (Gal-beta-1,4-GlcNAc-R) chains with similar efficiency. Displays species-dependent substrate specificity. Participates in galactose sulfation and shows substrate preference for structures such as lactose, lacto-N-tetraose (Lc4), lacto-N-neotetraose (nLc4), the Gal-beta-1,4-GlcNAc-beta unit in mucin core-2, and the cancer antigen Globo H precursor Gal-beta-1,3-GlcNAc-beta-1,3-Gal-R.
Synonyms: Gal3ST-2; GP3ST
Tractability: Antibody: UniProt predicts a signal peptide or a membrane-spanning region.
Gene: Protein-coding gene on chromosome 2 (241,776,822 to 241,804,287, forward strand). Ensembl gene ENSG00000154252.
Subcellular location: Golgi apparatus, Golgi stack membrane
Gene Ontology:
Molecular function: galactose 3-O-sulfotransferase activity; protein binding; galactosylceramide sulfotransferase activity
Biological process: glycoprotein biosynthetic process; glycolipid biosynthetic process
Cellular component: membrane; Golgi cisterna membrane
Genetic constraint (gnomAD): Loss-of-function variants: 16 observed, 12.22 expected, observed/expected ratio (o/e) 1.31, 90% interval 0.88 to 1.85. The synonymous counts are far from expectation, so gnomAD's model fits this gene poorly and the ratio says little. Missense variants: 635 observed, 508.76 expected, observed/expected ratio (o/e) 1.25, 90% interval 1.17 to 1.33. Synonymous variants: 300 observed, 241.63 expected, observed/expected ratio (o/e) 1.24, 90% interval 1.13 to 1.37.
Homologues: Orthologues: chimpanzee GAL3ST2 (97% identical), macaque GAL3ST2 (89% identical), pig GAL3ST2 (75% identical), rabbit GAL3ST2 (74% identical), mouse Gal3st2 (68% identical), mouse Gal3st2b (68% identical), rat Gal3st2c (68% identical), mouse Gal3st2c (67% identical), zebrafish gal3st2 (48% identical), tropical clawed frog gal3st2 (40% identical). Paralogues in human: GAL3ST4 (43% identical), GAL3ST3 (36% identical), GAL3ST1 (35% identical).
Diseases named in the same sentence as GAL3ST2 in open-access papers:
GAL3ST2 is named in the same sentence as 17 diseases in open-access papers, as found by Europe PMC text mining. Sharing a sentence is not in itself a finding about the gene and the disease. The quoted sentences say what the papers report.
colorectal cancer (3 papers, 2023 to 2024). A primary or metastatic malignant neoplasm that affects the colon or rectum. "Conversely, B3GNT7 and GAL3ST2 were downregulated and were protective factors in colorectal cancer." (PMID 39309424, 2024).
allergic asthma (1 paper, 2024). A asthma with a basis in a pathological type I hypersensitivity reaction. "The genes associated with mucin production (GAL3ST2), leukotriene synthesis (GPX4), Th2-mediated allergic asthma (PTBP1, ZFPM1, SBNO2, and EGFL7), and IgE mediated allergy (PAK2) were also represented in our polygenic prediction models of ICS response." (PMID 38540988, 2024).
breast carcinoma (1 paper, 2022). "With respect to the O-GalNAc pathway, we observed alterations in several related glycogenes including the downregulation of GCNT4, GALNT13, GALNT16 and C1GALT1, and upregulation of ST3GAL1, ST6GALNAC4 and GAL3ST2 in Her2+ breast cancer tissue." (PMID 36282863, 2022).
gastric cancer (1 paper, 2016). A primary or metastatic malignant neoplasm involving the stomach. "The GAL3ST-2 has been shown to be involved in CRC and gastric cancer while GAL3ST-1 has only been suggested to be involved in ovarian cancer." (PMID 26872740, 2016).
cancer (4 papers, 2015 to 2021). A tumor composed of atypical neoplastic, often pleomorphic cells that invade other tissues. "For malignant tumor, the expression of Gal3ST2 was even further attenuated in poorly differentiated tissue." (PMID 34555499, 2021).
tumor (1 paper, 2021). "Our TMA study showed that protein expression levels of sulfotransferases Gal3ST4 and CHST1 remained the same in serous ovarian tissue from all tumor stages and degree of differentiation, whereas Gal3ST2 levels were decreased in malignant tissue." (PMID 34555499, 2021).
GAL3ST2 also shares sentences with these, for which no sentence is quoted: prostate carcinoma (4 papers); Bladder cancer (2); cervical cancer (2); esophageal cancer (2); esophageal squamous cell carcinoma (2); Allergy (1); asthma (1); autism (1); cognitive decline (1); ovarian adenocarcinoma (1); ovarian carcinoma (1).